AHR (aryl hydrocarbon receptor)
Diseases named in the same sentence as AHR in open-access papers (continued):
Sharing a sentence is not in itself a finding about the gene and the disease.
Sepsis (18 papers, 2014 to 2025). Sepsis is defined as life-threatening organ dysfunction caused by a dysregulated host response to infection. "The upregulation of ileal AhR-associated gene expression after sepsis suggests AhR signaling is activated when cholecalciferol and/or calcitriol were administered." (PMID 36079813, 2022). "In animal models, IPA is found to effectively ameliorate left heart dysfunction and myocardial inflammation associated with sepsis by modulating the AhR/NF-κB/NLRP3 (aryl hydrocarbon receptor/nuclear factor-kappaB/NOD-like receptor protein 3) signaling pathway." (PMID 40078933, 2025). "AhR-dependent reduction in bacterial burden, protection against organ damage, and decreased sepsis-related mortality following IPA administration were shown." (PMID 40942152, 2025). "First, the effects of IPA were reversed in vivo by an AhR antagonist, as demonstrated, e.g., in a murine sepsis model." (PMID 40942152, 2025). "As shown in a cell culture sepsis model, downregulation of AhR results in a decreased CYP1A2 expression in hepatocytes." (PMID 38589754, 2024). "An LPS-induced sepsis model, generated by intraperitoneal injection of AhR+/+ and AhR-/- mice with LPS (20 mg/kg), was used to confirm the function of AhR in acute inflammation in vivo." (PMID 39113799, 2024). "It prevents acute lung injury in sepsis by regulating intestinal microbiota and restoring intestinal barrier through aryl hydrocarbon receptor/NRF2-dependent pathway, and also regulates the rationality of neuroimmune interaction to exert analgesic effects." (PMID 37388447, 2023). "In this study, we investigated the role of IPA-induced AhR activation in controlling the infection during sepsis using the cecal ligation and puncture (CLP) model in mice." (PMID 36299625, 2022). "Aryl hydrocarbon receptor (AhR) highly specific inhibitor (CH223191) was used to observe the role of AhR in the protection of IPA against sepsis." (PMID 36299625, 2022). "The research covered in this report showed that genetic ablation of CYP1A1 contributes to intestinal barrier protection against MRSA-induced sepsis by shifting the microbiota composition to decrease cadaverine metabolite levels in a non-AHR-dependent manner." (PMID 35572636, 2022). "IPA is a protective factor for sepsis through improving survival and host control of infection by partially promoting aryl hydrocarbon receptor-dependent macrophages phagocytosis." (PMID 36299625, 2022). "Then, in animal model, IPA administration protected against sepsis-related mortality and alleviated sepsis-induced bacterial burden and organ injury, which was blunted by AhR inhibitor." (PMID 36299625, 2022). "Kynurenine is a tryptophan breakdown product and ligand of the aryl hydrocarbon receptor (AhR), which protects the host in multiple models of malaria and sepsis." (PMID 34607466, 2021). "Our findings reveal a novel role for the IDO1/Kyn/AhR pathway in ferroptosis, suggesting that targeting this pathway may offer a promising therapeutic strategy for sepsis." (PMID 40715082, 2025). "Targeting the IDO1/Kyn/AhR axis may provide a promising therapeutic strategy to restore T cell immunity and improve outcomes for patients with sepsis." (PMID 40715082, 2025). "Mechanistically, our findings reveal that inflammatory signals upregulate IDO1 expression, which drives Kyn accumulation, leading to lipid oxidation-related gene transcription via activation of the AhR and ultimately resulting in thymocyte ferroptosis during sepsis." (PMID 40715082, 2025). "The correlation of VD/AhR and intestinal integrity during sepsis is worthy of investigation." (PMID 36079813, 2022). "Both oral cholecalciferol before and IV calcitriol after CLP promoted cathelicidin secretion, alleviated intestinal inflammation, and ameliorated the epithelial integrity in obese mice complicated with sepsis possibly via VD receptor and AhR signaling pathways." (PMID 36079813, 2022).
Sepsis (continued). "In human medicine, AHR function is of relevance for toxicity response, inflammation, autoimmune disorders, cancer, circadian clock and for sensing bacterial virulence and thereby activate antibacterial responses and control sepsis." (PMID 33274714, 2020). "The significance of IDO induced AhR-mediated effects on sepsis has still to be investigated." (PMID 26881062, 2015). "It has been shown that increased concentrations of KYN or KYNA, both ligands of AhR, and increased concentrations of TGF-β and IL-6 are risk factors for establishment of an immunoparalysis and for a poor prognosis of patients in early sepsis instead of recovery." (PMID 26881062, 2015). "Thus, we aimed to elucidate whether IPA played a protective role in sepsis was related to AhR." (PMID 36299625, 2022). "Intriguingly, we previously reported the possible AHR-independent regulation of CYP1A1 expression and CYP1A1-induced proinflammatory responses during the progression of inflammation and sepsis." (PMID 35572636, 2022). "Notably, in the ongoing sepsis of nonsurvivors (day 7), IL-6 did not significantly decrease in plasma, enabling the autocrine activation of IDO via the AhR-IL-6-STAT3 loop as described in human cells." (PMID 26881062, 2015).
type 2 diabetes (18 papers, 2010 to 2025). "Our findings provide evidence that LTBI is associated with an increase in circulating AhR levels in patients with type 2 diabetes." (PMID 40508196, 2025). "Our main finding in the present study was that high serum AhR levels were significantly associated with LTBI in patients with type 2 diabetes." (PMID 40508196, 2025). "LTBI, confirmed by a QFT-positive result, is associated with an increase in serum AhR levels in patients with type 2 diabetes." (PMID 40508196, 2025). "Exposure to environment-polluting chemicals (EPCs), which are ligands of the aryl hydrocarbon receptor (AhR), is associated with the development of type 2 diabetes (T2D)." (PMID 39596044, 2024). "In conclusion, in patients with type 2 diabetes, a high serum AhR level was associated with LTBI." (PMID 40508196, 2025). "Such AhR-driven changes are advocated as accounting for the heightened severity and fatality that are associated with preexisting, high-risk medical conditions, such as type 2 diabetes." (PMID 34230210, 2021). "Coffee consumption, mainly driven by SNPs in the CYP1A1/2 and AHR genes which are also associated with higher caffeine intake but lower blood caffeine metabolites, was positively associated with type 2 diabetes in the inverse-variance weighted and weighted median models." (PMID 32895727, 2020). "Another study showed that indoleacrylic acid (an indole derivative) alleviates type 2 diabetes by activating the aryl hydrocarbon receptor (AhR), which reduces IL-1β, IL-6, and TNF-α levels." (PMID 41156481, 2025). "The aggregate literature compellingly implicates PPAR-α signaling, AhR activation, and circadian clock dysfunction in the development of type 2 diabetes in humans after exposure to environmental toxicants." (PMID 21849270, 2011). "This study provides important insight into mechanisms by which toxicants, acting through AhR, produce type 2 diabetes." (PMID 21849270, 2011). "Third, our experiments demonstrated that IA could alleviate type 2 diabetes by activating AhR to repair the intestinal barrier in vitro, but in vivo experiments were needed to further verify this conclusion." (PMID 37072819, 2023). "This could have important implications for how individuals with islet inflammation, including those with type 2 diabetes, respond to environmental chemicals that activate AhR signalling." (PMID 31776611, 2020). "The role of the AhR in SARS-CoV-2 severity/fatality is supported by data regarding the pre-existing high-risk medical conditions for SARS-CoV-2 severity/fatality, including obesity, type II diabetes, CVDs, and old age." (PMID 32867244, 2020). "Therefore, our data suggest that neither an AhR affinity nor estrogenicity explain the association between PCBs and type 2 diabetes." (PMID 20444671, 2010). "We aimed to examine the relationship between serum levels of aryl hydrocarbon receptor (AhR) and LTBI in patients with type 2 diabetes." (PMID 40508196, 2025). "Thus, mechanisms other than AhR affinity may be involved in the pathogenesis of type 2 diabetes." (PMID 20444671, 2010). "In this study, therefore, we aimed to detect LTBI among outpatients with type 2 diabetes and to assess the serum AhR levels between patients with and without LTBI." (PMID 40508196, 2025). "Although aryl hydrocarbon receptor (AhR) affinity has been the main focus in relation to POPs toxicity, PCBs with some affinity to AhR (PCB105, PCB118, and PCB156) were not clearly associated with the risk of type 2 diabetes." (PMID 20444671, 2010).
immunotoxicity (17 papers, 2010 to 2026). "This AhR activation leads to gene responses and causes immunotoxicity, endocrine disruption, and oxidative stress." (PMID 42197259, 2026). "The majority of biological effects of TCDD leading to immunotoxicity and associated deleterious effects are mediated by aryl hydrocarbon receptor (AhR)." (PMID 23024791, 2012). "It has been demonstrated that AHR plays an important role in modulating the response to many microbial pathogens, and the abnormal expression of AHR signaling pathways may disrupt endocrine, cause immunotoxicity, and even lead to the occurrence of cancer." (PMID 36829212, 2023). "The common feature of all dioxin-like compounds is their high affinity to the aryl hydrocarbon receptor (AHR), which mediates their characteristic toxic effects, such as developmental defects, endocrine disruption and immunotoxicity." (PMID 39226334, 2024). "It has been described that the activation of the AhR can induce immunotoxicity, including thymic involution." (PMID 36831795, 2023). "Vice versa, research on AhR-mediated immunotoxicity will advance basic knowledge of fish immunology." (PMID 34502366, 2021). "Exposure to dioxins such as TCDD has previously been shown to inhibit NF-κB expression in an AHR-dependent manner, inducing sustained immunosuppression and immunotoxicity." (PMID 34769237, 2021). "This question clearly warrants further research to elucidate if there is a role of the microbiome in AhR-related immunotoxicity in fishes." (PMID 34502366, 2021). "Dioxins induce toxic effects on laboratory animal such as wasting syndrome, tumorigenicity and immunotoxicity, and the mechanisms are believed to involve the activation of the aryl hydrocarbon receptor (AhR)." (PMID 22911699, 2012). "However, dysregulated AhR expression can result in endocrine disorders, leading to immunotoxicity and potentially promoting the development of carcinoma." (PMID 38680494, 2024). "Pollution toxic agents may also activate the aryl hydrocarbon receptor (AhR), chronic activation of which may lead to immunotoxicity." (PMID 36094704, 2022). "Second, while for mammals it is well documented that the binding of contaminants to the AhR causes immunotoxicity, we do not know if this mechanism is active in fish as well." (PMID 34502366, 2021). "Upon miR analysis, we observed several miRs that were downregulated (>1.5-fold) in thymocytes post-TCDD exposure thereby indicating that these miRs may be associated with regulation of AhR and CYP1A1 vis-a-vis immunotoxicity." (PMID 23024791, 2012). "In addition, Aroclors and ortho-substituted PCBs contain or are partial agonists that suppress TCDD-induced immunotoxicity, presumably through competitive binding to the AhR." (PMID 20435556, 2010). "In addition, there is evidence that PCDEs may induce immunotoxicity through the mediation of the aryl hydrocarbon receptor (AHR)." (PMID 36900991, 2023). "We hypothesized that CD5+ ILBs may be sensitive to AHR-mediated immunotoxicity." (PMID 33936048, 2021). "Activation of the AhR pathway by environmental contaminants induces a battery of genes involved in the biotransformation of xenobiotics, and it can lead to diverse toxic responses including developmental abnormalities, cancer promotion, liver and renal failure, and immunotoxicity." (PMID 32878328, 2020). "AhR signaling has been shown to be an important player in TCDD-induced thymic atrophy and immunotoxicity." (PMID 23024791, 2012). "Moreover, for CDE 77, 101, 118, 126, 153 and 156, an excellent linear correlation was observed between their immunotoxicity and induced ethoxyresorufin-O-deethylase (EROD) or aryl hydrocarbon hydroxylase (AHH) activity as markers of AHR activation in mice (Mus musculus)." (PMID 36900991, 2023).
lymphoma (16 papers, 2015 to 2024). A malignant (clonal) proliferation of B- lymphocytes or T- lymphocytes which involves the lymph nodes, bone marrow and/or extranodal sites. "Treatment with TCDD led to the loss of apoptosis response in three lymphoma cell lines through the downregulation of B-cell lymphoma-extra-large (Bcl-xL) and myeloid cell leukemia-1 (mcl-1), which was abrogated with an AhR antagonist." (PMID 38339226, 2024). "For example, the loss of AhR expression in NK cells resulted in reduced cytolytic activity and control of lymphoma growth, while in vivo administration of the endogenous ligand 6-formylindolo[3,2-b]carbazole (FICZ) enhanced AhR-dependent antitumor activity in these cells." (PMID 37106727, 2023). "The aryl hydrocarbon receptor (AhR) is known for mediating the toxicity of environmental pollutants such as dioxins and numerous dioxin-like compounds, and is associated with the promotion of various malignancies, including lymphoma." (PMID 31035533, 2019). "NK cells from AhR-deficient mice had poorer cytotoxic activity against RMA-S lymphoma cells as compared to NK cells from wild-type mice, treating animals with the potent AhR ligand 6-formylindolo (3,2-b) carbazole (FICZ) enhanced NK cell control of RMA-S tumors." (PMID 30808363, 2019). "Cytokine stimulation with interleukin (IL) 2, IL15, or IL12 induced AhR expression in NK cells of mice in vitro, while knockout of AhR in NK cells reduced their cytolytic activity and ability to control lymphoma formation." (PMID 38339226, 2024). "The important role of IL-1β has also been demonstrated in AhR-mediated (TCDD-induced) development of lymphoma." (PMID 37696458, 2023). "In line with this, an important role of IL-1β has been identified in inflammation-induced and AhR-dependent tumor promotion of lymphoma in mice." (PMID 37696458, 2023). "Although AHR was found in many cancers (24% of all tumors) and specific tumor types (for example, 55% of cases of malignant lymphoma), it contributed to a minority of UPD events, most of which were progressive (31% P-UPD versus 1% AHR-UPD by total width)." (PMID 37945902, 2023). "As a corollary, AHR activation with TCDD inhibited apoptosis in lymphoma cells in vitro and in vivo through the induction of COX2 and dysregulation of BCL2." (PMID 33396563, 2020). "In particular, many studies demonstrated elevated AhR levels and constitutive activity in a variety of cancer cell lines and B lineage malignancies including lymphomas, myelomas and T cell leukemia." (PMID 25669983, 2015). "Human exposure to the xenobiotic AhR agonist TCDD and PCBs is associated with increased incidence of lymphoma and leukemia, and low dose TCDD promotes lymphoma development in mice." (PMID 26208102, 2015). "In addition, the expression of AhR, CYP1A1, CYP1B1, RUNX1 and SLC7A8 was upregulated in MEPs of individuals with lymphoma, concomitant with enhanced nuclear localization of AhR." (PMID 37919525, 2023). "Moreover, we reported that the effects on cancer cell proliferation were accompanied by autophagy induction, as well as demethylation within the aryl hydrocarbon receptor gene promoter in the lymphoma RAJI cell line." (PMID 30572618, 2018). "Our previous studies found that C/EBPβ and COX-2 are important mediators of an AhR-dependent and TCDD-induced resistance to apoptosis in lymphoma cells, demonstrating their critical role in AhR-driven tumor cell survival." (PMID 33763068, 2021). "We have previously shown, that C/EBPβ and COX-2 are important mediators of an AhR-dependent and TCDD-induced resistance to an apoptotic response in lymphoma cells demonstrating the critical role of COX-2 in the pathogenesis of lymphoma." (PMID 31035533, 2019). "AhR is emerging as a tumor modulator in hematological malignancies, including acute myeloid leukemia (AML), multiple myeloma, chronic lymphocytic leukemia (CLL), and lymphomas, where its precise roles are just beginning to be understood." (PMID 38807762, 2024).
lymphoma (continued). "Thus, AhR has been shown to interact with one sub-unit of the mitochondrial F0F1-ATPase, namely the ATP5a1, in several cell lines (hepatic cells, lymphoma cells)." (PMID 37696458, 2023). "As would be predicted from this understanding of AHR activity, mice lacking these hydroxylases were shown to have a lower incidence of malignant lymphomas and other tumors induced, for example, by PAH." (PMID 33396563, 2020). "In summary, our data indicate that the tumor suppressive function of AhRR is mediated via its interaction with the non-canonical AhR pathway resulting in down-regulation of cellular inflammation through inhibition of the PKA-C/EBPβ inflammatory axis and inhibition of tumor growth and lymphoma." (PMID 31035533, 2019).